WT1 (WT1 transcription factor)
Diseases named in the same sentence as WT1 in open-access papers (continued):
Sharing a sentence is not in itself a finding about the gene and the disease.
breast carcinoma (continued). "The inhibition on proliferation of breast cancer cells by WT1–ZF - KTS provides a potential candidate of gene therapy for breast cancer." (PMID 17634147, 2007). "There is growing evidence that the Wilms' tumor 1 suppressor gene (WT1) behaves as an oncogene in some forms of breast cancer." (PMID 17634147, 2007). "In this manuscript we show that WT1–ZF can behave as a dominant negative of WT1 in WT1-expressing breast cancer cells." (PMID 17634147, 2007). "Consistent with the ability to suppress the expression of genes important for cell growth and survival, transfection of WT1–ZF - KTS into the breast cancer cell line MCF-7 had a marked effect on cell behavior." (PMID 17634147, 2007). "This binding and inhibition is significant as we found decreased expression of WT1 mRNA and protein in the breast cancer cell lines transfected with WT1–ZF." (PMID 17634147, 2007). "For this reason we assessed the effect of WT1–ZF on the expression of WT1 itself, and on the expression of Bcl-2 and c-myc in the context of WT1-expressing breast cancer cell lines." (PMID 17634147, 2007). "We also tested the effect of full-length WT1 and WT1–ZF in the WT1-negative breast cancer cell line MDA231." (PMID 17634147, 2007). "Transfection with WT1–ZF plasmids resulted in a stronger inhibition of WT1 promoter than full-length WT1 in breast cancer cells." (PMID 17634147, 2007). "These constructs were then co-transfected with either full-length WT1 or WT1–ZF expression plasmids into the WT1-expressing breast cancer cells MCF-7 or MDA468." (PMID 17634147, 2007). "In keeping with this observation, we also showed that the expressions of two other WT1 targets, Bcl-2 and c-myc, are repressed by WT1–ZF in breast cancer cell lines." (PMID 17634147, 2007). "For example, in Hela cells, WT1 inhibits the transactivation of c-myc – while in the breast cancer cell line MDA468, WT1 activates c-myc expression." (PMID 17634147, 2007). "We note that despite tumour-specific WT1 promoter methylation in primary breast cancer, WT1 protein is still expressed in these tumours." (PMID 15505628, 2004). "Additionally, the target genes were also enriched in the binding motif of Wilms' tumor 1 (WT1), a developmental transcription factor commonly dysregulated in hematologic malignancies and solid tumors such as breast cancer, ovarian cancer and glioblastoma." (PMID 38308491, 2024). "Previous reports have established that WT1 might activate MYC transcription in breast cancer and lung cancer cells." (PMID 37667197, 2023). "Similarly, in breast cancer, WT1-positive tumors were found to be more mesenchymal, and overexpression of WT1 in breast epithelial cells, HBL100, led to upregulation of mesenchymal markers, such as Vimentin (Vim) and Tenascin C (Tnc)." (PMID 36864480, 2023). "Wilm’s tumor gene 1 (WT1) is oncogenic as well as a tumor suppressor in breast cancer." (PMID 36699376, 2022). "However, it was demonstrated by subsequent studies that WT1 was related to the disruption of the EMT signaling pathway and docetaxel resistance in breast cancer, high expression of WT1 also corresponded to a lower overall survival." (PMID 34513664, 2021). "According to the results, EDN2, CLEC3B, SV2C, and WT1 could significantly influence the prognosis of breast cancer patients." (PMID 34513664, 2021). "Accordingly, based on these previous studies, we hypothesize that overexpression of wt1 and a change in isoform allow WT1 to be present at different stages of breast cancer progression." (PMID 34845427, 2021). "WT1 protein is overexpressed in more than 90% of breast cancer; however, its role during tumor progression is still unknown." (PMID 34845427, 2021). "Overexpression of CLEC3B and WT1 could dramatically promote the formation of colonies in breast cancer cells." (PMID 34513664, 2021). "It was found that CLEC3B and WT1 could markedly enhance the capability of growth and migration in breast cancer cell lines." (PMID 34513664, 2021).
breast carcinoma (continued). "In the present study, we analyzed the WT1 isoforms present in breast cancer cell lines." (PMID 34845427, 2021). "As HER2 plays an important role in the stemness maintain of breast cancer stem cells, WT1 may play a role in maintaining the biological characteristics of breast cancer stem cells." (PMID 32210734, 2020). "Women with WT1 methylation presented a 1.62 higher risk of luminal A and 2.23 higher risk of luminal B subtype of breast cancer than those without methylation." (PMID 32736539, 2020). "We found that high WT1 mRNA expression was associated with high histological grade, estrogen receptor (ER)-negative status, basal-like subtype, and ERBB2 (erb-b2 receptor tyrosine kinase 2, HER2) subtype in breast cancer patients." (PMID 32210734, 2020). "The hypermethylation of WT1 is associated with an increased risk of luminal subtypes of breast cancer, and the hypermethylation of CA10 is associated with an increased risk of luminal B subtype of breast cancer." (PMID 32736539, 2020). "It is important to determine whether WT1 plays a significant role in the invasion, migration, and metastasis of breast cancer and explore its molecular mechanism." (PMID 32210734, 2020). "Besides, multivariate analysis showed that WT1 was an independent indicator of poor prognosis for breast cancer patients." (PMID 32210734, 2020). "In summary, the results of our study suggested that methylation of WT1, CA10 in blood leukocytes may be associated with the risk of breast cancer." (PMID 32736539, 2020). "MicroRNA-193a expression in breast cancer was negatively correlated with WT1 expression, and overexpression of WT1 could partially offset the activity of microRNA-193a." (PMID 32210734, 2020). "Although WT1 has been originally identified as a tumor suppressor, it is also overexpressed in a variety of human cancers, including acute leukemias and solid tumors like breast cancer." (PMID 31058089, 2019). "This investigation addressed the hypothesis that WT1 expression is increased in vascular endothelial cells in human breast cancers." (PMID 30374123, 2018). "We hypothesised that WT1 expression would vary in endothelial cells in distinct sub-classifications of breast cancer." (PMID 30374123, 2018). "This investigation addressed the hypothesis that WT1 expression is increased in endothelial cells in human breast cancers." (PMID 30374123, 2018). "However, whilst WT1 expression is increased in breast cancers, this increase cannot be attributed solely to increased expression in the endothelium." (PMID 30374123, 2018). "In addition, the numbers of vessels, and WT1-positive vessels were also higher in Grade I breast cancers compared to Grade II tumours." (PMID 30374123, 2018). "miR-193a and WT1 expression were significantly inversely correlated in breast cancer tissues." (PMID 29016617, 2017). "Lastly, examination of WT1 expression in a panel of thirteen breast cancer cell lines by qPCR demonstrated that seven of the cell lines had detectable levels of WT1, with the highest expression observed in the basal triple-negative lines HBL100 and MDA-MB-157 and in the luminal ER+ line ZR75." (PMID 28345629, 2017). "In the MDA-MB-157 line the percentage of CD44+/CD24− cells did not change significantly upon WT1 loss, suggesting that down-regulation of WT1 does not affect the ‘stemness’ of breast cancer cells." (PMID 28345629, 2017). "The negative correlation between miR-193a expression and WT1 indicates that patients with breast cancer who have lower miR-193a expression may have higher WT1 expression, which might contribute to the activation of carcinogenesis and invasion." (PMID 29016617, 2017). "Given this association between WT1 and CYP3A4 expression in breast cancer, we decided to investigate whether the tumour levels of WT1 can be used to predict the response of breast cancer patients to docetaxel." (PMID 28345629, 2017).
breast carcinoma (continued). "miR-193a and WT1 expression levels and the clinical parameters of 25 breast cancer specimens." (PMID 29016617, 2017). "Here, we report interaction between miR-193a and WT1 in breast cancer." (PMID 29016617, 2017). "Therefore, further investigation of WT1 as a potential target of chemotherapy for breast cancer is warranted." (PMID 26573232, 2016). "In previous work, we investigated whether methylation of the CpG island surrounding the WT1 promoter influenced WT1 expression in breast cancer." (PMID 25794157, 2015). "Wilm’s Tumor 1 Receptor WT1 has also been described as an interesting marker to make the differential diagnosis between a metastasis from ovarian origin and a breast primary, although some breast cancers have been found positive for WT118,19." (PMID 25566350, 2014). "Interestingly, genes with frequent methylation in male breast cancer (MSH6, CDH13, PAX5, PAX6 and WT1) were also very commonly methylated in female breast cancer." (PMID 22765268, 2012). "Finally, the inhibitory effect of WT1–ZF - KTS on breast cancer growth supports the development of such a molecule or other inhibitors of WT1 in the control of breast cancer and other malignancies characterized by WT1 overexpression." (PMID 17634147, 2007). "Therefore, upregulating the expression of WT1 protein may be an effective strategy for treating breast cancer." (PMID 38742454, 2024). "Thus, this GATA3-MGP-TRPS1 panel may need inclusion with Pax-8 and WT-1 to differentiate breast carcinoma from serous carcinoma." (PMID 36284362, 2022). "The heatmaps of the 10 HR−/HER2+ breast cancers were homogeneous, while for 9 HR-/HER2− cases, a major cluster with ATM, FGFR1, and WT1 frameshift mutations (n = 6 for ATM1, FGFR1 and n = 5 for WT1) and a minor one with JAK3 splice site mutations were prominent (n = 3)." (PMID 34203389, 2021). "Moreover, the 36-38 kDa WT1 isoform was expressed in all breast cancer cells." (PMID 34845427, 2021). "Therefore, the results confirm that wild-type WT1 acts as an oncogene in breast cancer." (PMID 32210734, 2020). "However, associations between the methylation of the zinc-related genes, WT1 and CA10, and breast cancer risk remain unknown." (PMID 32736539, 2020). "The results of our study indicated that after PS adjustment, WT1 methylation was associated with the risk of luminal A and luminal B subtypes of breast cancer with ORs of 2.62 and 3.23, and CA10 methylation was significantly associated with luminal B subtype of breast cancer with OR of 1.80." (PMID 32736539, 2020). "Therefore, elucidation of the WT1 regulatory mechanism in breast cancer is important." (PMID 29016617, 2017). "Because DNA methylation plays a prominent role in this process, and in regulating tumor-specific silencing of tumor suppressor genes, we have previously investigated whether the methylation status of the CpG island surrounding the WT1 promoter influences expression in breast cancer." (PMID 25794157, 2015). "The ability of WT1–ZF to reduce/block the expression of genes such as c-myc, Bcl-2, AREG and WT1 itself, genes important for the survival and proliferation of breast cancer cells, raised the possibility that WT1–ZF could impair the growth of breast cancer cells." (PMID 17634147, 2007). "Thus, in breast cancer, higher ELF3 or lower WT1 levels associated with worse outcomes, while in colorectal and ovarian cancer, lower ELF3 or higher WT1 levels had worse prognosis, reminiscent of the antagonistic role of ELF3 and WT1 in mediating phenotypic plasticity." (PMID 36864480, 2023). "This study developed a signature featuring 8 OARGs (HLA-B, RBBP8, SPRY4, WT1, WWOX, UPRT, PELO, ZNF208) and determined its prognostic and functional implications in breast cancer patients." (PMID 36960071, 2023). "HER2 has been shown to upregulate WT1 expression through the AKT signaling pathway, promoting breast cancer cell proliferation and inhibiting cellular apoptosis." (PMID 35465313, 2022).
breast carcinoma (continued). "WT1 peptide vaccine is known to induce clinical responses in MDS, AML, CML, ALL, multiple myeloma and various types of solid tumors including lung and breast cancers." (PMID 35465313, 2022). "Of the five biomarkers, three genes (EDN2, WT1, and MUC2) were upregulated in the breast cancer samples while CLEC3B and SV2C were decreased." (PMID 34513664, 2021). "We screened out five protein coding genes (EDN2, CLEC3B, SV2C, WT1, and MUC2) significantly corresponding to the overall survival time of patients with breast cancer in the training group." (PMID 34513664, 2021). "Out of all breast cancer subtypes examined, TNBC had the highest WT1 expression, with WT1 expression (score > 2+) being recorded in 27 (54%) TNBC cases, but only 6 (12%) and 3 (6%) of ER-positive and HER2-positive tumour cases, respectively." (PMID 34359776, 2021). "One of the truncated WT1 isoforms was also detected in some types of cancer such as prostate cancer cell line, K562 (myeloid leukemia cell line), MCF-7 (breast cancer cell line), and acute leukemic blood samples." (PMID 33110919, 2020). "WT1 is constitutively expressed in AML, CML, and MDS as well as in solid tumors such as breast cancer, and WT1+CTLs have been identified in peripheral blood of patients." (PMID 30622438, 2019). "Several guidelines recommended GCDFP-15 and mammaglobin staining in cases of suspected breast cancer, while PAX-8 and WT-1 are recommended IHC markers for CUP with suspected ovarian cancer." (PMID 29433539, 2018). "Direct bisulfite sequencing also showed widespread methylation occurring in intragenic regions of the WT1, PAX6 and ITGA4 genes and in the promoter region of the OTX2 gene in breast cancer tissues." (PMID 26121976, 2015). "The established breast cancer relevance for AREG, WT1, and IER3 is discussed in a previous transcript profiling study." (PMID 23758962, 2013). "Methylation is involved in the development of female breast cancer, with frequent methylation of PAX6, BRCA2, PAX5, WT1, CDH13 and MSH6 in ductal carcinoma in situ and invasive ductal cancer." (PMID 22765268, 2012). "The abundances of endogenous WT1 mRNA and protein were markedly decreased following the stable expression of ZF - KTS in breast cancer cells." (PMID 17634147, 2007). "ZNF224, besides its function as a transcriptional regulator in breast cancer and CLL, acts as a cofactor of the protein of Wilms tumor (WT1) and, in such a manner, can regulate WT1 apoptotic target genes in chronic myelogenous leukemia (CML) cells to exert a tumor‐suppressive role." (PMID 40321146, 2025). "Initially, the expression of 52-54 kDa protein isoform of WT1 in the breast cancer cell line ER (+) was detected by western blot and was absent in ER (-), and the 36-38 kDa protein isoform of WT1 was detected in all cell lines analyzed." (PMID 34845427, 2021). "Although discounted by different sample-derived DNA, the significant negative correlations between WT1, CA10 methylation and gene expression were consistent with our study and indicated promising potential in breast cancer risk assessment." (PMID 32736539, 2020). "Breast cancer samples also exhibited a combination of vessels that did not express WT1, alongside those containing WT1-positive (endothelial and smooth muscle) cells." (PMID 30374123, 2018). "WT1 expression was significantly upregulated in breast carcinoma tissues compared to that in the adjacent non-cancerous tissues." (PMID 29016617, 2017). "Our study also shows that the adjacent non-cancerous tissues had low levels of WT1 as compared with the breast cancer tissue." (PMID 29016617, 2017). "Although the relationship between WT1 and breast cancer has been studied, the biological significance of WT1 signaling in breast cancer has not been completely elucidated." (PMID 29016617, 2017). "Similarly, in breast cancer cells, the estrogen receptor enhances IGF-IR gene promoter activity via interactions with Sp1 and WT1." (PMID 25884514, 2015).
breast carcinoma (continued). "On the other hand, mammary tumors with high levels of WT1 have a poor prognosis and high levels of WT1 expression are frequently observed in cases of breast cancer that are estrogen and progesterone receptor negative." (PMID 24955840, 2014). "For instance, Bax expression was significantly decreased by either of the two WT1 isoforms in breast cancer cells, whereas it was not changed in leukemic cells." (PMID 25491731, 2014). "In this analysis, we used organ-specific antibodies, including TTF-1 for lung cancer, WT-1 or PAX8 for gynecological cancers, mammaglobin or GCDFP-15 for breast cancer, PSA for prostate cancer, CDX2 for gastrointestinal cancers, and uroplakin for urothelial cancers." (PMID 22299055, 2012). "In our studies carried out in WT1-expressing breast cancer cell lines, the co-transfection of WT1 along with reporter constructs neither inhibited nor stimulated WT1 promoter reporter expression." (PMID 17634147, 2007). "In the breast cancer study, observed that a high expression of WT1 conferred a poor prognosis for breast cancer patients independent of other conventional prognostic factors." (PMID 19455234, 2007). "In breast carcinoma, ER IHC stain was positive, and WT1 was negative, favoring breast origin." (PMID 36938247, 2023). "WT1 aberrant methylation may lead to a reduction or absence of WT1 expression, which results in the overexpression of the insulin-like growth factor I receptor (IGF 1R) and insulin-like growth factor II (IGF II), thereby promoting breast cancer process." (PMID 32736539, 2020). "Our data illustrating an accumulation of β-catenin upon a reduction of WT1 in leukemic cells corresponds to an observed negative impact of WT1 on β-catenin signaling in breast cancer cells, Sertoli cells forming the blood-testis barrier, and podocytes within the kidney." (PMID 31561534, 2019). "In the current study, we used MCF-7 breast cancer cell line to determine the effect of EFA-CLA, as potential ligands for peroxisome proliferator-activated receptors (PPARs), on identified in silico PPAR-responsive genes: BCAR3, TCF20, WT1, ZNF621, and THRB (transcript TRβ2)." (PMID 28458685, 2017). "WT1, CA 125, and PAX8 are usually positive in high-grade serous ovarian carcinoma and negative in breast carcinoma; however, in some cases of breast cancer, CA 125 and WT1 also might be positive." (PMID 28730323, 2017). "Summarising the differences in cellular and vascular expression of WT1 demonstrated that Grade II and III, but notably not Grade I, breast cancers exhibited greater expression of WT1-positive cells than matched-control tissue." (PMID 30374123, 2018).